HCG25 (HLA complex group 25)
Synonyms: dJ1033B10.16
Gene: Long non-coding RNA gene on chromosome 6 (33,248,510 to 33,260,681, forward strand). Ensembl gene ENSG00000232940.
Diseases named in the same sentence as HCG25 in open-access papers:
HCG25 is named in the same sentence as 4 diseases in open-access papers, as found by Europe PMC text mining. Sharing a sentence is not in itself a finding about the gene and the disease. The quoted sentences say what the papers report.
breast carcinoma (1 paper, 2023). "Research has shown that HCG25 is upregulated in liver cancer and A1BG-AS1 to be highly expressed in breast cancer tissues and cell lines." (PMID 36874406, 2023).
cancer (2 papers, 2020 to 2023). A tumor composed of atypical neoplastic, often pleomorphic cells that invade other tissues. "HCG25, A1BG-AS1, DBH-AS1, RUSC1-AS137, RAMP2-AS1, LINC00893, and LINC00894 are genes that are currently being studied mainly in cancer." (PMID 36874406, 2023).
HCG25 also shares sentences with these, for which no sentence is quoted: liver cancer (1 paper); type 2 diabetes (1).